NPY (neuropeptide Y)
Diseases named in the same sentence as NPY in open-access papers (continued):
Sharing a sentence is not in itself a finding about the gene and the disease.
epilepsy (60 papers, 2008 to 2025). A brain disorder characterized by episodes of abnormally increased neuronal discharge resulting in transient episodes of sensory or motor neurological dysfunction, or psychic dysfunction. "In gene therapy for epilepsy, the use of AAVs encoding potassium channel or NPY genes are the most investigated." (PMID 35645733, 2022). "In epilepsy cases overall, the relative loss of CR and NPY positive interneurones was less than principal pyramidal neuronal loss in CA1 and CA4, whereas equal or greater relative loss of CB-positive interneurones was noted." (PMID 22608064, 2012). "Altogether, the combined results of our CB and NPY labelings, and the previous association of these markers with epilepsy, suggest, albeit indirectly, that a large proportion of Dcx KO mice may have experienced recurrent spontaneous epileptic seizures." (PMID 18575605, 2008). "NPY binds to presynaptic Y2 or Y5 receptors, reducing glutamate release and addressing the excitatory-inhibitory imbalance in epilepsy." (PMID 40310132, 2025). "In a study where the effect of AAV-induced long-lasting NPY overexpression in the hippocampus in different models of epilepsy in rats was investigated, the expression pattern of NPY under the NSE promoter was AAV serotype-dependent." (PMID 39937026, 2025). "Nonetheless, these data demonstrate that overexpression of NPY and Y2R in DG GCs is sufficient to exert a robust anti-seizure effect in a genetic model of epilepsy." (PMID 39251828, 2024). "Many pre-clinical studies in multiple genetic and induced models of epilepsy have tested NPY-based gene therapy products." (PMID 39251828, 2024). "Gene therapy with AAV vectors carrying genes for neuropeptide Y and its receptor Y2 has been shown to inhibit seizures in multiple animal models of epilepsy." (PMID 37029201, 2023). "As such, neuropeptide Y, which indirectly inhibits presynaptic glutamate release, has been shown to be upregulated in patients with resistant epilepsy and rodent models." (PMID 34716961, 2022). "Particularly the expression of neuropeptide Y (NPY) is strongly enhanced in animal models of epilepsy and human temporal lobe epilepsy (TLE)." (PMID 36311021, 2022). "In animal models of epilepsy and in human TLE, recurrent seizures cause marked overexpression of NPY in GABA-ergic interneurons and in glutamatergic mossy fibers." (PMID 36311021, 2022). "SVHRP upregulated the mRNA and protein levels of BDNF and NPY, providing a potential candidate for epilepsy treatment." (PMID 33825777, 2021). "Using lentivirus, adeno-associated virus, and herpes simplex viral vectors in animal models, the most gene therapies for treatment of epilepsy targeted neurotrophic factors, galanin, adenosine kinase, and neuropeptide Y." (PMID 32440322, 2020). "In the context of epilepsy, NPY is thought to act as an endogenous anticonvulsant that performs its action through Y2 and Y5 receptors." (PMID 33551745, 2020). "As described in this review, all studies on gene therapy-mediated overexpression of NPY and/or its receptors in epilepsy models have been performed by using AAV vectors." (PMID 33551745, 2020). "NPY has been recently proposed for gene therapy, depending upon patient data, to control epilepsy using various viral vector carriers." (PMID 31708779, 2019). "This proof-of-concept finding is an important translational milestone for validating NPY-based gene therapy for targeting focal drug-resistant epilepsies, and increasing the prospects for positive outcome in potential clinical trials." (PMID 31852985, 2019). "Understanding the regulation of AC-cAMP-CREB signaling and the expression of NPY is expected to elucidate the efficacy of TCM in the treatment of epilepsy and should provide the basis for the development of new Chinese medicines." (PMID 31915447, 2019).
epilepsy (continued). "It is known that the morphology of neuropeptide Y-positive neurons with regard to the average length of the longest neurite is significantly shorter in infants with perinatal brain injury and this may contribute to the predisposition to epilepsy in premature infants." (PMID 31178744, 2019). "Both in acute and chronic epilepsy models, transgenic NPY results in a remarkable antiepileptic effect when overexpressed in the hippocampus or piriform cortex by rAAV vectors." (PMID 31915447, 2019). "But the results of Vezzani and Sperk showed that NPY expression in epilepsy was higher than in the control group, which was different from our results." (PMID 31915447, 2019). "The anticonvulsant effect of NPY gene overexpression in rat brains shows the important role in controlling epilepsy of NPY." (PMID 31708779, 2019). "We kept the resected tissue slices alive in vitro for 48 h to create a platform for testing a novel treatment strategy based on neuropeptide Y (NPY) against drug-resistant epilepsy." (PMID 31852985, 2019). "NPY play a significant role in regulating various physiological events in the brain, including energy balance, learning and memory, and epilepsy." (PMID 28824436, 2017). "NPY also play a significant role in human epilepsy and it is supported by an increased NPY expression in biopsy samples from temporal lobe epilepsy patients." (PMID 28824436, 2017). "Such ectopic expression of NPY has been reported in Tg2576, hAPPJ20, and APPswexPS1dE9 mice, arguing for the existence of epilepsy in these AD models." (PMID 25768013, 2015). "NPY, somatostatin, galanin and dynorphin have endogenous anti-convulsant properties with protective effects against epilepsy, whereas substance P has a pro-epileptic effect." (PMID 24762203, 2014). "During seizures NPY is strongly upregulated and the release of NPY is increased in the regions of the seizure, as shown in several animal models as well as in epilepsy patients." (PMID 24705860, 2014). "In particular, peptide hormones such as adiponectin, ghrelin, and leptin and neuropeptides such as CCK, galanin, NPY, and somatostatin appear to be promising candidates for future research on new treatments for epilepsy." (PMID 24808888, 2014). "Those anti-epileptic effects were cancelled by administration of NPY Y2 receptor antagonist, which indicates that therapeutic effects of EPO against epilepsy were mediated at least partially by NPY." (PMID 24287913, 2013). "Further evidence for the importance of NPY in epilepsy has come from NPY knockout and transgenic mice." (PMID 24039965, 2013). "Continuous intrahippocampal administration of BDNF likely attenuated the development of epilepsy mainly through increased expression of neuropeptide Y (NPY)." (PMID 24287913, 2013). "A recent study demonstrated that intraventricular NPY infusion exerted neuroprotective and neurogeneic effects against experimental epilepsy." (PMID 24287913, 2013). "Indeed, we provide here evidence that a biased expression of Y2R and NPY in hippocampal GCs is sufficient to exert a significant seizure-suppressant effect in a genetic model of epilepsy, the TKO." (PMID 39251828, 2024). "In the present work, we show that overexpression of NPY and its Y2R in hippocampal excitatory neurons (in our settings, predominantly in DG GCs) exerts robust anti-seizure effects in the Synapsin triple-KO model of epilepsy." (PMID 39251828, 2024). "Interestingly, we found that downregulation of ΔFosB in the dorsal hippocampus during the chronic phase of epilepsy after pilocarpine-induced SE decreased NPY staining in the dentate gyrus." (PMID 38283700, 2023). "This hypothesis is currently used in the field as a basis for exploiting NPY in gene therapy for epilepsy." (PMID 38283700, 2023).
epilepsy (continued). "The current focus of gene therapy strategies for epilepsy is primarily aimed at reducing neuronal excitability by overexpressing neuro-modulatory peptides such as neuropeptide Y, galanin etc. or by the genetic modification of astrocytes, for example, to suppress adenosine kinase (ADK) expression." (PMID 35645733, 2022). "Decreased levels of neuropeptide Y, a neurotransmitter, act through multiple unique mechanisms, such as inhibiting intracellular Ca2+ accumulation and acting as an anti-inflammatory, also implemented in the worsening progression of poststroke epilepsy." (PMID 36338344, 2022). "Therefore, in this study, we established a new animal model of epilepsy-induced SC and demonstrated how NPY affects cardiac dysfunction in the SC model." (PMID 36408384, 2022). "In this study, we demonstrated that upstream sympathetic activation could induce significant upregulation of NPY in left SG and cardiac sympathetic nerves, resulting in cardiac dysfunction like SC by using a new animal model of epilepsy-induced SC." (PMID 36408384, 2022). "The increase in NPY expression was detected in the granule cells by immunohistochemistry and in situ hybridization, proving the alteration of the granule cell phenotype in epilepsy." (PMID 35008630, 2021). "The increased synthesis and release of NPY are widely reported in animal models and patients with epilepsy, suggesting that NPY signaling could also modulate key aspects of the cortical E/I imbalance during critical stages of ALS disease pathogenesis." (PMID 34439588, 2021). "A consistent amount of data demonstrates the functional involvement of the NPY system in epilepsy." (PMID 33551745, 2020). "Early attempts in this direction explored the anti-seizure potential of NPY overexpression mediated by rAAV serotype 2 (rAAV2) vector injection in the hippocampus or piriform cortex in the rat kainate model of epilepsy." (PMID 33551745, 2020). "NPY is a 36-amino acid peptides and is among the most studied neuropeptides in epilepsy." (PMID 33732146, 2020). "Taken together, these data suggest a significant involvement of NPY in the epileptogenic process, supporting the idea that both pharmacological and genetic approaches targeting the NPY system may represent effective strategies for the treatment of epilepsy." (PMID 33551745, 2020). "The present review will summarize data related to NPY biology, focusing on its anti-epileptic effects, with a critical appraisal of key elements that could be exploited to improve the already existing NPY-based gene therapy approaches for epilepsy." (PMID 33551745, 2020). "Many studies have established the seizure-suppressant effects of NPY against seizures in the hippocampus both in rodents and hippocampal slices from pharmacoresistant human epilepsy patients." (PMID 33343295, 2020). "After HJSD-H treatment, the expression of adenylate cyclase (AC), cyclic adenosine monophosphate (cAMP), cAMP-response element binding protein (CREB), and neuropeptide Y (NPY) immunoreactive cells markedly increased in the hippocampus, compared with that of the epilepsy group (P < 0.05)." (PMID 31915447, 2019). "Indeed, there is a strong correlation between what has been observed in in vitro animal models of epileptiform activity with in vivo (both acute and chronic) epilepsy models in terms of NPY-mediated inhibition of seizure activity." (PMID 31852985, 2019). "However, EMB treated fish showed increases in NPY expression, indicating that it plays a crucial role in modulating neurotransmitters, increasing neuronal growth, and preventing epilepsy in zebrafish brains." (PMID 31708779, 2019). "NPY is an inhibitory neuromodulator normally expressed by a subset of hippocampal interneurons, which can be expressed ectopically in mossy fibers after chronic seizures in animal models of epilepsy." (PMID 25768013, 2015). "The NPY system is also involved in epilepsy, which is known to increase adult neurogenesis acutely." (PMID 24516629, 2014).
epilepsy (continued). "The NPY is also an endogenous anti-seizure compound, which has been evidenced through its upregulation in response to status epilepticus, occurences of seizure activity with reduced NPY levels and reduced epileptiform-like activity with NPY treatment in epilepsy prototypes." (PMID 25620912, 2014). "Since ghrelin is a promising candidate in view of its modulatory properties in seizures, the changes in this hormone regulation found in patients with epilepsy are of major interest, whereas other changes in peptide hormone regulation, involving leptin, galanin, and NPY, must be clearly defined." (PMID 24808888, 2014). "Neuropeptide Y (NPY) is one of the most studied neuropeptides in epilepsy." (PMID 24705860, 2014). "Analysis of all sections from epilepsy cases, sides and levels showed a significant correlation between pyramidal cell neuronal density as quantified with CV and interneuronal numbers for CR (p < 0.01), CB (p < 0.0001) and NPY (p < 0.005) in CA4." (PMID 22608064, 2012). "Further investigation of estrogen and NPY in relation to epilepsy may be promising in the search for effective antiepileptic therapies." (PMID 21390307, 2011). "Therefore, inhibition of BDNF/TrkB signaling and induction of neuropeptide Y (NPY) expression may reduce seizure frequency and severity in patients with epilepsy." (PMID 38006577, 2024). "Interestingly, NPY immunoreactivity was increased in the granule cell mossy fiber pathway (hilus and stratum lucidum) in some Vgat ablation mice, consistent with previous studies demonstrating production of NPY by granule cells in epilepsy models." (PMID 38575351, 2024). "Therefore, NPY-based gene therapy may be a new anti-epileptic agent for the management of resistance epilepsy." (PMID 38006577, 2024). "Interestingly, in hippocampal tissue resected from epilepsy patients, NPY and the Y2 receptors are upregulated, suggesting that it may be an endogenous response to counteract hyper-excitability." (PMID 37029201, 2023). "Thus, also in humans NPY may mediate epileptic tolerance, and enhancing NPY-Y2 receptor mediated transmission may be an effective strategy for antiepileptic treatment for epilepsies in humans." (PMID 36311021, 2022). "However, conventional antiepileptic drugs are ineffective in treating epilepsy; administration of exogenous NPY may provide an alternative therapy by inhibiting seizure activity before more invasive neurosurgery is indicated." (PMID 36338344, 2022). "Several peripheral peptide hormones involved in the control of food intake and metabolism (e.g., leptin, adiponectin, NPY, insulin, ghrelin) that are influenced by the KD also possess antiseizure properties and, as such, are promising candidates for future research on new treatments for epilepsy." (PMID 35276837, 2022). "Moreover, inhibiting BDNF-TrkB signaling and simultaneous activation of the NPY system could become a new treatment pathway for epilepsy." (PMID 33802323, 2021). "In models of epilepsy and in lines of mice expressing hAPP or specific hAPP metabolites, chronic epileptiform activity leads to molecular alterations in the hippocampus, including reduced expression of calbindin and c-Fos and increased expression of NPY in dentate granule cells." (PMID 33833046, 2021). "Y1R may be responsible of unfavorable effects in epilepsy, because administration of Y1R antagonists produces antiepileptic effects in animal models and Y1 KO mice display reduced mortality rate upon NPY administration." (PMID 33551745, 2020). "Therefore, NPY-based gene therapy may represent a novel approach for the treatment of epilepsy patients, particularly for pharmaco-resistant and genetic forms of the disease." (PMID 33551745, 2020). "Thus, NPY in the DG has been proposed to be an important factor in the modulation of epilepsy." (PMID 27630542, 2016).
epilepsy (continued). "In addition, it has been recently recognized that NPY also regulates hippocampal neurogenesis, indicating roles beyond seizure modulation 97 but that may be relevant to cognitive decline in epilepsy." (PMID 24762203, 2014). "Thus we may speculate that micro-environmental changes induced by epilepsy and/or neurodegeneration could strengthen the NPY-mediated influence on the hippocampal niche, thus promoting significant neurogenic outcomes." (PMID 24516629, 2014). "Another gene therapy approach targets neuromodulatory peptides, particularly neuropeptide Y (NPY), which has shown promising results in reducing seizure frequency by up to 40% in various epilepsy models." (PMID 40310132, 2025). "The soma of many NPY+ neurons in the SE+NSC group also exhibited hypertrophy (Fig. 5C2), likely implying enhanced activity of these interneurons in the chronic phase of epilepsy." (PMID 33269095, 2020). "This is because the excitatory granule cells, which in epilepsy give rise to mossy fiber sprouting (MFS), have been demonstrated to ectopically produce and release NPY." (PMID 33551745, 2020). "Few studies have investigated the role of genes such as neuropeptide Y (NPY) gene, CREB1, and brain-derived neurotrophic factor (BDNF) that interact with each other to control epilepsy and enhance long term memory." (PMID 31708779, 2019). "Our results showed that NPY expression in the epileptic rats was significantly lower than the control group, and the HJSD-H group was significantly higher than that in the epilepsy group." (PMID 31915447, 2019). "However, the neurotrophic and neuroprotective properties of BDNF can be potentially used to treat epilepsy, e.g., by inhibiting BDNF-TrkB signaling and reinforcing the NPY system." (PMID 38069144, 2023). "In relation to epilepsy, NPY-positive cells in the dentate gyrus have not been studied as extensively as SOM-positive cells." (PMID 27092056, 2016). "To investigate the functional integration of newly-born neurons, here we studied in adult rats the long-term effects of intracerebroventricular administration of NPY (2 μg/2 μl, 4 days after TMT-treatment), which plays an adjuvant role in neurodegeneration and epilepsy." (PMID 24516629, 2014). "The overexpression of NPY driven by the CMV promoter, with an AAV vector injected intracerebroventricularly (i.c.v.), prolonged seizure latency and decreased seizure severity up to 4 weeks after the injection in the rat model of kainic acid (KA)-induced epilepsy." (PMID 39937026, 2025). "Besides NPY a variety of other parameters of GABA-ergic neurons, e.g., glutamate decarboxylase (GAD1 and 2), somatostatin (SOM) or cholecystokinin (CCK-8) are dynamically altered in animal models of epilepsy." (PMID 36311021, 2022). "However, overexpression of NPY is known to result in the expression of the N-methyl-D-aspartate receptor subunits NR1, NR2A, and NR2B, which plays a critical role in the development of epilepsy." (PMID 35645733, 2022). "Conversely, experiments on hippocampal slices from an animal model of epilepsy (pilocarpine-treated rats) show that NPY does not affect the response of granule cells to perforant path stimulation but reversibly inhibits recurrent synaptic transmission of mossy fibers on granule cells themselves." (PMID 33551745, 2020). "Also, in our previous study, we demonstrated high numbers of NPY-Y1R+ degenerating axons in infarct tissue while axonal degeneration was virtually absent in epilepsy patients." (PMID 23354834, 2013).